CHI3L1 (chitinase 3 like 1)
Diseases named in the same sentence as CHI3L1 in open-access papers (continued):
Sharing a sentence is not in itself a finding about the gene and the disease.
cancer (continued). "In summary, CHI3L1 plays a central role in inflammation-associated cancers." (PMID 40643503, 2025). "Taken together, these findings indicate that CHI3L1 plays a central role in the progression and of multiple inflammation-associated cancers and may function both as a biomarker and a therapeutic target." (PMID 40643503, 2025). "CHI3L1 has been implicated in various biological processes and diseases, including cancer." (PMID 39033204, 2024). "Additionally, CHI3L1 has been associated with various cancers and rheumatoid arthritis, confirming its role as an unspecific inflammatory marker." (PMID 39768177, 2024). "This suggests a broad spectrum of anti-cancer activity associated with CHI3L1 inhibition." (PMID 39399677, 2024). "Recent studies suggest that the involvement of CHI3L1 in inflammation-associated cancer progression may be related to the cell surface target receptors." (PMID 39068486, 2024). "Therefore, inhibiting CHI3L1 expression is expected to be a new prevention and treatment strategy for chronic inflammation as well as inflammation-associated cancer." (PMID 38667293, 2024). "We investigated how CHI3L1 causes ER stress in normal cells and cancer cells." (PMID 37215572, 2023). "Thus, we first examined the inhibitory effects of K284 in CBD‐mutated CHI3L1‐transfected cancer cells, by assessing the cell proliferation." (PMID 34758182, 2022). "Chitinase 3‐like protein 1 (CHI3L1) is most likely a malignant tumor metastasis‐associated gene." (PMID 31536166, 2020). "Compared to primary LC, cancer cells of LC-BoM were nearly all LC_cells_3 which was characterized by chitinase-3-like 1 (CHI3L1) expression." (PMID 41362730, 2026). "The CHI3L1 protein supports various types of cancer progression and metastasis, where the background players were the upregulation of angiogenesis and microenvironment modulation." (PMID 42062601, 2026). "They suggested that targeting CHI3L1 can reactivate the antitumor immune response and improve responses to ICIs in cancer." (PMID 40900789, 2025). "This occurs through both autocrine and paracrine mechanisms, with CHI3L1 being secreted by both cancer cells and macrophages." (PMID 40643503, 2025). "Chitinase-3-like protein 1 (CHI3L1) is a secreted glycoprotein that is upregulated in several cancers." (PMID 40900789, 2025). "Immunotherapy is a conventional treatment for solid tumors, and CHI3L1 has played a role in the T cell-based cancer immunotherapies." (PMID 40821115, 2025). "As a key mediator of the inflammation–cancer axis, CHI3L1 is emerging as a novel and promising target for cancer therapy." (PMID 40643503, 2025). "These astrocytes additionally secrete Chitinase 3-like-1 (CHI3L1), inducing cancer cell invasion into the brain." (PMID 39858080, 2025). "During inflammation, cardiovascular diseases, fibrosis, cancer, neurodegenerative diseases, or parasitic invasions, the serum level of CHI3L1 can increase to more than 100 ng mL−1." (PMID 40313579, 2025). "Numerous cells have been reported to secrete CHI3L1, including activated neutrophils, macrophages, vascular smooth muscle cells, chondrocytes, and cancer cells." (PMID 40013912, 2025). "The protein CHI3L1 contributes to cancer development by several mechanisms, including stimulation of angiogenesis and invasion as well as immunomodulatory effects." (PMID 39607670, 2025). "CHI3L1 is a molecule that plays a central role in the crosstalk between cancer and inflammation, and its functional significance has been clarified through studies using genetically engineered or chemically induced mouse models." (PMID 40643503, 2025). "This review summarizes the significance of CHI3L1 as a potential target in multiple inflammatory diseases and cancer by analyzing data from platforms like Open Targets and other data-analysis tools." (PMID 38177294, 2024). "One of the proteins involved in angiogenesis in most cancers is CHI3L1 (YKL-40), which remains a potential candidate for anti-angiogenesis treatment." (PMID 39399677, 2024).
cancer (continued). "A previous study indicated that cancer cells secrete CHI3L1 into the TME and recruit M2 macrophages for reprogramming." (PMID 39574472, 2024). "The most investigated CLP family member in the context of cancer is CHI3L1, being of specific interest due to its conserved expression in both mice and humans." (PMID 38605414, 2024). "CHI3L1, also known as YKL-40, is a secreted glycoprotein that plays a role in cancer cell growth, proliferation, invasion, metastasis, and angiogenesis." (PMID 38773224, 2024). "CHI3L1 antibodies have earned considerable interest among researchers for their potential application in cancer therapy." (PMID 38667293, 2024). "Antibody-based therapies also facilitate the immune-mediated clearance of CHI3L1(YKL40)-expressing cancer cells." (PMID 38543093, 2024). "While the precise mechanism connecting inflammation and cancer is unclear, the involvement of CHI3L1 is involved in chronic inflammation, suggesting its role as a contributing factor to in the link between inflammation and cancer." (PMID 39068486, 2024). "Their continuous studies of CHI3L1 in various inflammatory disorders as well as malignant diseases revealed that CHI3L1 was produced by inflammatory cells and cancer cells by regulating cell proliferation, differentiation, and extracellular tissue remodeling." (PMID 38667293, 2024). "The expression of CHI3L1 expression is upregulated in several malignant tumors, underscoring the crucial role of chronic inflammation in the initiation and progression of cancer." (PMID 39068486, 2024). "The expression of CHI3L1/YKL-40 serves as an adverse prognostic indicator in many cancers and inflammatory diseases." (PMID 38672496, 2024). "YKL-39 is present only in humans and plays a role in chronic inflammatory and neurodegenerative diseases; its proangiogenic role in cancer was discovered after that of CHI3L1." (PMID 39068486, 2024). "The protein CHI3L1 supports cancer development in several ways, including stimulation of angiogenesis and invasion as well as immunomodulatory effects." (PMID 39399677, 2024). "Strategies that target CHI3L1 for the treatment of cancer recently have recently demonstrated progress in preclinical studies." (PMID 39068486, 2024). "CHI3L1 interacts with the interleukin-13 receptor α2 chain on the membrane of cancer cells, activating the mitogen-activated protein kinase signaling pathway." (PMID 39185402, 2024). "Chitinase-3-like protein 1 (CHI3L1), a 39 kDa slip-membrane protein, is an inflammatory glycoprotein in various human cancers." (PMID 39026176, 2024). "The impacts of CHI3L1(YKL40)-targeted therapy on various diseases and cancer treatment strategies remain to be elucidated." (PMID 38543093, 2024). "Several clinical studies reported that the elevated expression of Chitinase-3-like 1 (CHI3L1) was observed in patients suffering from a wide range of diseases: cancer, metabolic, and neurological diseases." (PMID 38791588, 2024). "Several studies have indicated that serum or plasma CHI3L1(YKL40) can be used as an indicator of treatment response and prognosis in cancer patients." (PMID 38543093, 2024). "A recent study uncovered a new mechanism of cancer immune evasion, which involves inhibiting NK cells’ cytotoxic granule machinery by chitinase-3-like protein 1 (CHI3L1)." (PMID 38533507, 2024). "Studies have shown that CHI3L1 plays critical roles in cancer cell growth, proliferation, invasion, metastasis, angiogenesis, and immunoregulation." (PMID 38304922, 2024). "Our previous work demonstrated that CHI3L1 is implicated in PDAC cellular resistance to gemcitabine, identifying CHI3L1 as a potential therapeutic target for the treatment of this type of cancer." (PMID 39225813, 2024). "CHI3L1 is involved in cancer progression by promoting angiogenesis, proliferation and migration of cancer cells and modulating the immunologic background of carcinogenesis." (PMID 39399677, 2024).
cancer (continued). "Some studies have been conducted or are currently ongoing to investigate the effects of therapy targeting CHI3L1(YKL-40) in the treatment of some medical diseases and various cancer diseases." (PMID 38962736, 2024). "Interfering RNA targeting CHI3L1 inhibits the drug resistance, proliferation, and invasion of cancer cells." (PMID 39068486, 2024). "In this article, we provide a comprehensive review of recent findings regarding the involvement of CHI3L1 in the development of inflammatory diseases and cancer." (PMID 38177294, 2024). "Levels of CHI3L1 mRNA and protein are significantly elevated in inflammatory diseases, cancer, and degenerative diseases and are closely associated with patient survival and poor prognosis." (PMID 38003338, 2023). "The role of Chi3L1 was also studied in a non-cancer context, such as fibrosis, where scientists observed its role in profibrotic macrophage activation, essential for progression of pathologic fibrosis, and fibroblast differentiation." (PMID 38313431, 2023). "Meanwhile, CHI3L1 advances the growth, proliferation, invasion, and metastasis of a variety of cancers." (PMID 37480002, 2023). "The close connection between CHI3L1 and cancer has been proposed by numerous researchers and is now well established." (PMID 38003338, 2023). "Increased CHI3L1 level is correlated with poor prognosis and decreased survival rate in cancer patients." (PMID 37340009, 2023). "In conjunction with these changes in expression, CHI3L1 was also highly expressed in lung tumor tissue from patients with cancer." (PMID 37215572, 2023). "These endeavors highlight the pivotal roles of CHI3L1 and suggest therapeutic approaches targeting CHI3L1 in the development of metabolic diseases, neurodegenerative diseases, and cancers." (PMID 38003338, 2023). "CHI3L1 has been reported to promote cancer growth, production of proinflammatory cytokines, and microglial activation." (PMID 36331721, 2023). "In this study, we compared the effect of CHI3L1 on the ER chaperone levels in normal cells and cancer cells." (PMID 37215572, 2023). "Over the past decade, significant attention has been directed towards exploring the potential role of CHI3L1 in the development of various human cancers." (PMID 37902124, 2023). "ER stress-mediated apoptosis induced by the depletion of CHI3L1 occurs in cancer cells, but rarely occurs in normal cells." (PMID 37215572, 2023). "Compared with control siRNA transfected-cells, apoptotic cancer cells were moderately increased in CHI3L1-depleted cells (1.31±0.52 vs 6.07±2.10%)." (PMID 37215572, 2023). "Elevated acute-phase biomarkers, such as the C-reactive protein (CRP) and YKL-40 (also called chitinase-3-like-1 protein, CHI3L1), are associated with a poor prognosis for various types of cancer, including CRC." (PMID 37047727, 2023). "CHI3L1 expression has been observed in various cancers, including breast, lung, colon, pancreatic, and even BLCA." (PMID 37958973, 2023). "Under thapsigargin induced stress, the depletion of CHI3L1 greatly eliminated cancer cell migration." (PMID 37215572, 2023). "Several studies have indicated high expression of CHI3L1 with tumor grade, unfavorable prognosis, and metastasis in various human cancer types." (PMID 37444617, 2023). "CHI3L1 is overexpressed in many human cancer types such as lung, liver, breast, colorectal, ovary and cervical cancers." (PMID 37902124, 2023). "Under stress conditions, the deficiency of CHI3L1 increased the PERK protein levels in both normal cells and cancer cells, but to a greater extent in cancer cells." (PMID 37215572, 2023). "YKL-40, also known as chitinase-3-like protein 1 (CHI3L1), is a secreted glycoprotein produced by various cell types including stromal, immune, and cancer cells." (PMID 37744345, 2023). "We then compared and analyzed the effect of CHI3L1 on the ER chaperon levels in normal lung cells and cancer cells." (PMID 37215572, 2023).
cancer (continued). "The proliferation of cancer cells transfected with CHI3L1 siRNA and treated with thapsigargin was significantly decreased (49.88±7.80%)." (PMID 37215572, 2023). "YKL-40 (cartilage glycoprotein-39; chitinase 3-like 1) is a secreted glycoprotein produced by inflammatory and cancer cells and has a role in inflammation, angiogenesis, and tissue remodeling." (PMID 37899440, 2023). "CHI3L1 is a secreted glycoprotein and a binding member of the mammalian chitinase-like proteins involved in various disorders, including cancer." (PMID 37444617, 2023). "Most of the CHI3L1 involved in cancer progression and regulation comes from macrophages, a group of cells that play an important immune role in the body." (PMID 38003338, 2023). "Chi3L1 is present in a healthy human body but increases in various diseases, including rheumatoid arthritis, osteoarthritis, and cancers." (PMID 34861103, 2022). "In the present study, we clarified that CHI3L1 was up-regulated at the mRNA level in 26 of 33 types of cancers in TCGA cohorts, especially in GBM." (PMID 36276655, 2022). "Our findings reveal the secretion mechanism of CHI3L1 and potential use of nCHI3L1 Ab for cancer treatment." (PMID 34987649, 2022). "Further research is required to obtain a comprehensive picture of the cancer-intrinsic CHI3L1 regulated by cytokines or growth factors involved in the cross talk between the stromal cells and cancer cells in TME." (PMID 34987649, 2022). "Many human cancers, such as breast, colon, prostate, lung, and liver cancers, have been reported to show increased CHI3L1 expression." (PMID 36615523, 2022). "Among the 11 compounds, K284 was selected as the candidate compound since it showed the strongest binding to CHI3L1 and the most significant cytotoxic effects against several cancer cell lines." (PMID 34758182, 2022). "The IF-IHC results in mouse allograft tumors prompted us to verify if tumors from cancer patients with high expression of both Rab37 and CHI3L1 (Rab37+CHI3L1+) also foster an immunosuppressive TME." (PMID 34987649, 2022). "In this paper, we propose that Chi3L1 is a good target therapeutic molecule for cancer and that anti‐Chi3L1 antibody requires clinical study." (PMID 34861103, 2022). "CHI3L1 secreted glycoprotein is known to play a significant role in the pathogenesis of Type 2-mediated inflammation and cancer; however, its trafficking mode remains undefined." (PMID 34987649, 2022). "Previous big data analysis studies have shown that CHI3L1 is a target protein close to several cancer outbreaks." (PMID 36615523, 2022). "Chi3L1 is expressed in many cancer cells and promotes cancer cell proliferation, macrophage recruitment, and blood vascular formation." (PMID 34861103, 2022). "To impair the protumor effects of CHI3L1, we further examined the function of nCHI3L1 Abs on cancer models including NSCLC cells H1299 and A549, PDAC cells PANC-1 and MIA PaCa-2 as well as CRC cells MC38." (PMID 34987649, 2022). "Many proteins (e.g., Interleukin-6 (IL-6) and YKL-40/chitinase 3-like 1 protein (CHI3L1)) secreted by cancer cells, macrophages, neutrophils, and fibroblasts stimulate inflammation." (PMID 35335885, 2022). "The high level of plasma CHI3L1 accompanied by poor prognosis of cancer patients suggesting that CHI3L1 is a biomarker of cancer progression as well as a therapeutic target in NSCLC, PDAC and CRC." (PMID 34987649, 2022). "YKL-40 (also named chitinase 3 like-1 protein [CHI3L1]) is a secreted chitinase-like protein which is upregulated in cancers and suggested to have pro-tumorigenic activity." (PMID 35631632, 2022). "CHI3L1 is expressed and secreted by a variety of cells, including macrophages, T cells, neutrophils, epithelial cells, smooth muscle cells, fibroblasts and cancer cells 1-5." (PMID 34987649, 2022). "Our in vitro and ex vivo data so far suggested that targeting CHI3L1 by nAbs inhibited cancer cell growth and migration and promoted immunostimulatory functions of T cells and macrophages." (PMID 34987649, 2022).
cancer (continued). "Despite extensive evidence for the role of CHI3L1 and IL‐13Rα carcinogenesis, studies of compounds preventing CHI3L1/13Rα signaling and consequently inhibiting cancer growth are limited." (PMID 34758182, 2022). "We have previously reported that Rab37 small GTPase mediates secretion of IL-6 in macrophages to promote cancer progression, whereas the roles of Rab37 in the intracellular trafficking and exocytosis of CHI3L1 are unclear." (PMID 34987649, 2022). "Overall, CHI3L1-induced MMP2 overexpression plays a crucial role in ECM regulation promoting cancer cell growth, proliferation, invasion, and metastasis." (PMID 33846436, 2021). "YKL-40 protein (coded by CHI3L1 gene) is highly expressed in a variety of malignant tumours, and its value in disease diagnosis, evaluation and prognosis judgement has attracted more and more attention." (PMID 34259106, 2021). "ADORA1 and the top 4 significant genes, including MYBPH, FAM178B, CHI3L1 and METTL7B were selected as the hub genes for genetic variation, interrelationship, cancer pathway and drug susceptibility analysis." (PMID 34093805, 2021). "We focused on CCL2 and VEGF-A as previous research suggested their molecular connection to CHI3L1 in the context of different cancers." (PMID 33920100, 2021). "The Chi3L1 gene is also involved in mediating inflammation, tissue remodeling, fat accumulation and cancer." (PMID 33498326, 2021). "Many proteins (e.g., Interleukin-6 (IL-6) and YKL-40/CHI3L1) secreted by cancer cells, macrophages, neutrophils and fibroblasts stimulate inflammation." (PMID 34200156, 2021). "CHI3L1 is overexpressed in different human cancers and CHI3L1 levels in PMF serum are increased, indicating that it is associated with disease progression from early-stage disease (ET, PV) to the myelofibrotic stage." (PMID 34905501, 2021). "Accordingly, our data suggest that the molecular targeting of CHI3L1 in the course of cancer immunotherapies can tune patients’ response and antitumoral inflammation." (PMID 33920100, 2021). "Previous studies have shown that Chi3L1 plays an important role in inflammation, tissue remodeling and cancer." (PMID 33498326, 2021). "In the 25 pair‐matched samples, CHI3L1 was markedly up‐regulated in cancer tissues compared with adjacent normal tissues (n = 25, P < .0001)." (PMID 31536166, 2020). "CHI3L1 (YKL40) is a secreted glycoprotein and elevated serum CHI3L1 level has been proved to be associated with poor prognosis in many human cancers." (PMID 30301907, 2018). "Human chitinase-3-like-protein-1 (CHI3L1, also known as YKL-40), an acute-phase glycoprotein, is elevated in cancers and inflammatory diseases but its clinical application remains restricted." (PMID 30276166, 2018). "Our data are consistent with previous finding that higher expression of CHI3L1 in sera of several types of cancers including breast, ovarian, colon and lung." (PMID 30301907, 2018). "Chitinase-3-like-1 (Chi3l1) is known to play a significant role in the pathogenesis of Type 2 inflammation and cancer." (PMID 29403003, 2018). "Accordingly, we found that the knockdown of CHI3L1 in HepG2 (HepG2-shCHI3L1) significantly decreased the ability of cancer cell migration (p < 0.01)." (PMID 30301907, 2018). "However, the mechanism of how CHI3L1 causes poor prognosis in cancers is still unknown." (PMID 30301907, 2018). "Chi3l1 is elevated in patients with a variety of tumors, and recent studies have suggested that Chi3l1 promotes cancers by enhancing cell proliferation, angiogenesis, etc28,42–44." (PMID 29403003, 2018). "YKL-40, also known as chitinase-3-like 1 protein and human cartilage glycoprotein 39, is produced locally by macrophages inside the vessel wall, vascular smooth muscle cells, arthritic chondrocytes, inflamed tissue, and cancer cells." (PMID 29686891, 2018). "As CD44 closely correlates with the oncogenesis and metastasis of various cancers, we then explored the molecular mechanism of CHI3L1/CD44 signaling in GC cells." (PMID 30165890, 2018).